HLA-DQA1 (major histocompatibility complex, class II, DQ alpha 1)
Diseases named in the same sentence as HLA-DQA1 in open-access papers (continued):
Sharing a sentence is not in itself a finding about the gene and the disease.
cervical carcinoma (10 papers, 2013 to 2024). A carcinoma arising from either the exocervical squamous epithelium or the endocervical glandular epithelium. "The significant association of HLA-DQA1 lead SNP (rs9272050) was replicated in invasive cervical cancer (p=7·90 × 10−8), CIN3 (p=0·0005), and cervical dysplasia (p=5·33 × 10−10) phenotypes." (PMID 33794208, 2021). "Three of these SNPs, PAX8 (rs10175462), CLPTM1L (rs27069) and HLA-DQA1 (rs9272050) were replicated in the independent Finnish dataset of 1648 invasive cervical cancer cases." (PMID 34683414, 2021). "Studies have reported that the haplotype HLA‐B*0702‐DRB1*1501/HLADQB1*0602 increases the risk of cervical carcinoma, whereas the haplotype HLA‐B*1501/HLA‐DRB1*1301/HLA‐DQA1*0103/HLA‐DQB1*0603 protects from the risk of the disease progression." (PMID 33586351, 2021). "Reduced risk of HPV18-associated cervical cancer was seen with HLA Class II alleles (HLA-DRB1*13 (OR = 0.51, P = 0.0058), HLA-DQB1*0603 (OR = 0.42, P = 0.021) and HLA-DQA1*0103 (OR = 0.50, P = 0.041))." (PMID 28806749, 2017). "Our study points to the importance of expression level of HLA-DQA1 and HLA-DQB1 for the susceptibility to develop cervical carcinoma." (PMID 27285765, 2016). "Several studies have previously shown associations between HLA alleles and cervical cancer, but not with HLA-DQA1." (PMID 36497170, 2022). "The UK Biobank cervical cancer GWAS, which combined CIN3 and invasive cervical cancer, confirmed variants at HLA-DQA1 (rs9272050), MICA (rs6938453), and HLA-DQB1 (rs55986091), of which HLA-DQA1 (rs9272050) was also replicated at a genome-wide significance in the FinnGen biobank cohort." (PMID 34680286, 2021). "Specifically, three haplotypes, HLA-DRB1*15/HLA-DQB1*0602/HLA-DQA1*0102, HLA-B*0702/HLA-C*0702 and HLA-DRB1*0401/HLA-DQA1*0301, were associated with increased risk of both HPV16 and HPV18-associated cervical cancer, and for the development of both squamous cell carcinoma and adenocarcinoma." (PMID 34683414, 2021). "Overall, three haplotypes, HLA-DRB1*15/HLA-DQB1*0602/HLA-DQA1*0102, HLA-B*0702/HLA-C*0702, and HLA-DRB1*0401/HLA-DQA1*0301, were associated with increased risk of both HPV16 and HPV18-associated cervical cancer, and for the development of both squamous cell carcinoma and adenocarcinoma." (PMID 28806749, 2017). "In addition, we confirmed associations with HLA-DRB1*15:01 and HLA-DQB1*06:02 as well as HLA-DRB1*13:01, HLA-DQA1*01:03 and HLA-DQB1*06:03, which are usually reported to be associated with risk of cervical cancer." (PMID 27285765, 2016). "We were able to replicate three SNPs in PAX8 (rs10175462), CLPTM1L (rs27069), and HLA-DQA1 (rs9272050) in an independent Finnish dataset of 4246 cervical dysplasia cases, 298 CIN3 cases, and 1648 cervical cancer cases (FinnGen)." (PMID 33794208, 2021). "Three SNPs were replicated in the independent Finnish dataset of 1648 invasive cervical cancer cases: PAX8 (rs10175462; p=0·015), CLPTM1L (rs27069; p=2·54 × 10−7), and HLA-DQA1 (rs9272050; p=7·90 × 10−8)." (PMID 33794208, 2021).
inflammatory bowel disease (10 papers, 2021 to 2026). A spectrum of small and large bowel inflammatory diseases of unknown etiology. "The PANTS consortium recently showed that the allele group HLA-DQA1*05 associates with the development of antibodies against infliximab in patients with inflammatory bowel diseases (IBD)." (PMID 34946883, 2021). "The human leukocyte antigen (HLA) allele group HLA-DQA1*05 predisposes to ulcerative colitis (UC) and is associated with the development of antibodies against infliximab in patients with inflammatory bowel disease (IBD)." (PMID 34946883, 2021). "Likewise, HLA-DQA1*15 has been linked to a lack of response to infliximab in inflammatory bowel disease (IBD)." (PMID 41026325, 2025).
Autoimmunity (9 papers, 2006 to 2025). The occurrence of an immune reaction against the organism's own cells or tissues. "Is it possible that the association with HLA-DQA1*04:01 is pointing to a role of autoimmunity and risk of BL." (PMID 38182727, 2024). "In the context of considering the pathogenesis of unexplained miscarriages and implantation failures as a result of systemic or local autoimmunity, the HLA-DQA1*5 allele has been implicated as a risk factor for these disorders." (PMID 36968684, 2023). "This study showed potential evidence that the HLA-DQA1 locus harbors a genetic risk factor for AAAs suggesting that autoimmunity plays a role in the pathogenesis of AAAs." (PMID 16879749, 2006). "The aim of the current study was to investigate further the role of autoimmunity in the etiology of AAAs by carrying out a genetic association study with the HLA-DQA1, -DQB1, and -DRB polymorphisms for AAA." (PMID 16879749, 2006). "Consequently, our principal findings are that the HLA-DQA1 or HLA-DQB1 complex is a critical entity that underlies the relationship between immunological reactions and the risk of developing SDNS/FRNS, which has a strong likelihood of being stimulated by autoimmunity or infection." (PMID 40087743, 2025). "In our study, HLA-DQA1 was also highly expressed in T1DM patients, suggesting that it may be involved in the pathogenesis of T1DM by inducing autoimmunity and could potentially be a therapeutic target." (PMID 34311758, 2021).
Crohn disease (9 papers, 2019 to 2025). A gastrointestinal disorder characterized by chronic inflammation involving all layers of the intestinal wall, noncaseating granulomas affecting the intestinal wall and regional lymph nodes, and transmural fibrosis. "In future studies, it would be valuable to investigate the relationship between HLA-DQA1*05 variant carriers and antibody formation using endoscopic indices (Crohn’s Disease Endoscopic Index of severity)." (PMID 39055374, 2024). "The HLA-DQA1*05 allele is also associated with anti-drug antibody production against biotherapies in Crohn’s disease patients, further contributing to its pro-inflammatory properties." (PMID 37407551, 2023). "HLA-DQA1*05 has been associated with GI-tract inflammation for many years, including raised symptom severity in ulcerative colitis (UC) and Crohn’s disease at diagnosis, in association with a more rapid onset, and an earlier need for immunosuppressive or biological treatment." (PMID 37407551, 2023). "The 2016 PANTS (Personalized Anti-TNF Therapy in Crohn’s disease) protocol, based on a three-year prospective study of over 1000 patients, established a strong link between HLA-DQA1*05 and anti-drug antibody development." (PMID 41153516, 2025). "It was hypothesized that the presence of HLA-DQA1*05 correlates with greater severity of ulcerative colitis (UC) and Crohn’s disease (CD) at diagnosis, more rapid onset, and earlier need for immunosuppressive or biological treatment." (PMID 34946883, 2021). "HLA-DQA1*05 was present in 221 (55.1%) out of 401 children with IBD (UC n = 188, Crohn’s disease n = 213)." (PMID 34946883, 2021).
systemic lupus erythematosus (9 papers, 2006 to 2024). An autoimmune multi-organ disease typically associated with vasculopathy and autoantibody production. "The lupus-associated variant in this SNP tags the lupus-associated classical alleles DRB1*03:01 and DRB1*15:01, and is associated with increased expression of HLA-DRB1, HLA-DQA1, and HLA-DQB1 in monocyte-derived dendritic cells." (PMID 35902632, 2022). "One high-LD SNP (rs9272422, r2 = 0.82 with our index SNP, rs660895) residing in the promoter region of HLA-DQA1 support this hypothesis and has been identified previously for systemic lupus erythematosus and ulcerative colitis." (PMID 33517400, 2021). "For example, FCGR3A, FCGR2B and HLA-DQA1 may function via the systemic lupus erythematosus pathway, and AMY2B and AMY2A may participate in lung SCC via starch and sucrose metabolism pathway." (PMID 26297502, 2015).
leprosy (8 papers, 2009 to 2024). Leprosy is a chronic infectious disease affecting primarily the skin and peripheral nervous system. "The CNV esv3608598 is a deletion in the intergenic region of HLA-DRB1 and HLA-DQA1, both of which have been reported to be associated with leprosy risk in many countries." (PMID 34976012, 2021). "Our team previously used the Han-MHC database as a reference panel for fine mapping and identified four independent sites associated with leprosy (HLA-DRβ1 amino acid Tyr26, HLA-C*08:01, HLA-DQA1*03:03)." (PMID 34976012, 2021). "Previously, two small studies reported a leprosy per se risk effect of HLA-DRB1*15:01 and a serotype linked to HLA-DQA1*01, and a well powered study of Brazilian leprosy patients detected a risk effect for both HLA-DRB1*10 and HLA-DRB1*15." (PMID 32776973, 2020). "Taken together the combined results of the present and previous studies strongly support the role of HLA-DRB1*10:01~ HLA-DQA1*01:05 as major leprosy risk factor in independent Indian and Vietnamese samples." (PMID 32776973, 2020). "A recent HLA imputation-based meta-analysis in the Chinese population identified HLA-DRB1 and HLA-DQA1 alleles and specific amino acids of HLA-DRβ1 as independent protective factors for leprosy." (PMID 32421744, 2020). "HLA-DQA1*01 was significantly associated with leprosy and presented frequencies of 43.1% and 32.8% in cases and controls, respectively (OR = 1.56, P = 8.34 × 10−7)." (PMID 32776973, 2020). "Among the leprosy per se associated HLA alleles, HLA-DQA1*01:05 presented the most significant evidence of association (OR = 3.11, P = 7.61 × 10−10) followed by HLA-DRB1*10:01 (OR = 3.08, P = 1.02 × 10−9)." (PMID 32776973, 2020). "When HLA-DQA1*01:05 entered as first independent genetic variable in the model, all HLA leprosy risk alleles lost significance." (PMID 32776973, 2020). "HLA-A, HLA-B, HLA-DQB1 and HLA-DQA1 alleles have also been reported to be associated with leprosy." (PMID 34976012, 2021). "In addition to HLA-DRB1, variants in HLA-DQA1 and HLA-C were also associated with leprosy in the Chinese population." (PMID 32776973, 2020). "Hence, HLA-DRB1*15:01 was indeed an independent leprosy risk factor for the Vietnamese patients which was also supported by the observation that HLA-DRB1*15:01 contributed significantly to leprosy risk independently of HLA-DRB1*10:01~ HLA-DQA1*01:05." (PMID 32776973, 2020). "It has been reported that leprosy-associated class II HLA genes include HLA-DRB1 in Vietnamese, HLA-DQA1/HLA-DPB1 in Brazilian, HLA-DQB1 in Mestizo, HLA-DRB1 in Argentinean, HLA-DRB1/HLA-DR-DQ in Chinese, and HLA-DQA1/HLA-DRB1 in Indian." (PMID 38440733, 2024). "Another study of genetic susceptibility to leprosy in India found rs1071630 located in HLA-DQA1 and rs9270650 in HLA-DRB1 associated with susceptibility to leprosy." (PMID 35664353, 2022). "In both the Vietnamese and the Chinese populations, HLA-DQB1*04:01 is part of a haplotype which includes HLA-DQA1*03:03 and HLA-DRB1*04:05, and in a meta-analysis of studies in Chinese patients HLA-DQA1*03:03 was identified as main leprosy resistance factor." (PMID 32776973, 2020). "Taken together, these results implicated HLA-DRB1*10:01/ HLA-DQA1*01:05 and HLA-DRB1*15:01 as strong global leprosy risk factors." (PMID 32776973, 2020). "The strongest leprosy susceptibility factors in our study were the HLA-DRB1*10:01 and HLA-DQA1*01:05 alleles which are in complete LD in the Vietnamese population." (PMID 32776973, 2020). "To test for leprosy associations independent of HLA-DRB1*10:01~ HLA-DQA1*01:05, we conducted a forward conditional association analysis of the 20 significantly associated alleles until markers presented Pconditional ≥ 0.01." (PMID 32776973, 2020). "Moreover, we replicated the previously associated HLA-DRB1*15:01 as leprosy risk factor and HLA-DRB1*04:05~HLA-DQA1*03:03 as protective alleles." (PMID 32776973, 2020).
leprosy (continued). "For this, we adjusted each of the formally non-significant HLA alleles on the presence of HLA-DQA1*01:05, HLA-C*07:06 and HLA-DRB1*12 and identified seven HLA four-digit alleles with evidence (Pconditional < 0.01) for association with leprosy." (PMID 32776973, 2020).
sarcoidosis (8 papers, 2012 to 2025). Sarcoidosis is a multisystemic disorder of unknown cause characterized by the formation of immune granulomas in involved organs. "A recent study utilizing a similar eQTL/GWAS approach (GTEx database) but restricted to ED-only sarcoidosis subjects, identified significant sarcoidosis-associated SNPs near HLA-DQA1, an HLA allele also identified by our eQTL/GWAS approach." (PMID 38390497, 2023). "Recently HLA-DRB1*03:01 and HLA-DQA1*05:01 alleles were associated with better prognosis in sarcoidosis, although MHC-related studies differ significantly among specific populations." (PMID 38390497, 2023). "Further, we suggest new HLA variants associated with sarcoidosis risk (e.g., HLA-DQA1*05:08) and novel protective variants HLA-DQB1*03:02 and HLA-DQA1*01:02 in Koreans." (PMID 35661780, 2022). "Concerning our observation of HLA-DQA1*05:01 associating with better prognosis, this variant was reported to be overrepresented in Japanese sarcoidosis patients compared with controls, and HLA-A*01:01 was reported with the resolving course of disease in Sweden." (PMID 37153085, 2023). "Regarding clinical phenotypes of sarcoidosis, HLA-A*01:01, HLA-B*08:01, HLA-C*07:01, HLA-DRB1*03:01, HLA-DQA1*05:01, and HLA-DQB1*02:01 associated with Löfgren’s syndrome." (PMID 37153085, 2023). "HLA-DQA1*05:03, HLA-DQA1*03:01, HLA-DQA1*05:01, and HLA-DQA1*01:01 were associated on the primary level as protective for sarcoidosis." (PMID 35661780, 2022). "We replicated associations for several previously reported sarcoidosis susceptibility risk loci in our AA collection including MHC Class II region genes (HLA-DRA, HLA-DRB5, HLA-DRB1, and HLA-DQA1), BTNL2, RAB23, and ANXA11." (PMID 22952805, 2012). "Therefore, in the context of the disease course, we can nominate HLA-DQA1*01:02 as a protective factor against sarcoidosis in Koreans." (PMID 35661780, 2022). "In that study, subsequent conditional analyses revealed four additional independent variants (SNPs rs146146117 HLA-DQA1, rs9461776 HLA-DRB1, rs715299 NOTCH4, and rs9272320 HLA-DQA1) associated with sarcoidosis risk in the HLA class II region at the suggestive GWA significance threshold." (PMID 24663488, 2014). "HLA-DRB1*01:01, HLA-DQA1*03:01, and HLA-DQB1*03:02 may confer protection against sarcoidosis: frequency of HLA-DRB1*01:01 decreased in the patients 2.5 times compared with the healthy control subjects, HLA-DQA1*03:01 dropped two times, and HLA-DQB1*03:02 4.5 times." (PMID 37153085, 2023). "HLA-DQA1 locus has not been mentioned in connection with sarcoidosis very often." (PMID 35661780, 2022).
hypothyroidism (7 papers, 2016 to 2025). Abnormally low levels of thyroid hormone. "This study is the first to reveal a causal relationship between hypothyroidism and cirrhosis, potentially driven by immune dysregulation mediated by HLA-DQA1 and CD27." (PMID 41202080, 2025). "In hypothyroidism, HLA-DQA1 maintained high diagnostic accuracy with an AUC of 0.924, whereas CD27, though more moderate, still achieved an AUC of 0.664." (PMID 41202080, 2025). "A recent GWAS in 56,664 individuals has identified other variant in HLA-DQA1 (rs17426593) associated with hypothyroidism." (PMID 39258111, 2024). "For hypothyroidism, the strongest 4-digit allelic associations were seen at the HLA-DQA1*0501, HLA-DQB1*0201, HLA-DRB1*0301 alleles (P<10−6 for each allele), which collectively comprise the HLA-DR3-DQ2 haplotype." (PMID 27109359, 2016). "We also report novel SNP associations for hypothyroidism near HLA-DQA1/HLA-DQB1 at rs6906021 (combined odds ratio (OR)=1.2 (95% confidence interval (CI): 1.1–1.2), P=9.8 × 10−11) and for polymyalgia rheumatica near C6orf10 at rs6910071 (OR=1.5 (95% CI: 1.3–1.6), P=1.3 × 10−10)." (PMID 27109359, 2016). "Notably, our study revealed that HLA-DQA1 may play a significant role in the process by which hypothyroidism promotes the risk of cirrhosis." (PMID 41202080, 2025). "This change in expression pattern suggests that hypothyroidism may participate in the development of cirrhosis by affecting HLA-DQA1 expression and altering the antigen presentation function of macrophages." (PMID 41202080, 2025). "Further correlation analysis between HLA-DQA1 and the gene sets linked to the top 10 key biological pathways revealed that CD27 stood out as the only gene showing both a strong correlation with HLA-DQA1 and consistent expression patterns across hypothyroidism and cirrhosis." (PMID 41202080, 2025). "In addition to HLA-DQA1, our study identified CD27 as another key molecule linking hypothyroidism and cirrhosis." (PMID 41202080, 2025). "Hypothyroidism has 4 genes (HLA-DPA1, HLA-DQB1, HLA-DQA1, and HLA-DPB1, where two have 5% of predictor variance each and two have 1% each) out of its top 17 genes included among the 641 potentially problematic genes, while 8% is the highest value of predictor variance accounted for by a single gene." (PMID 32694572, 2020).
membranous nephropathy (7 papers, 2017 to 2025). "A genome-wide association study has shown that variants in PLA2R1 and HLA-DQA1 are strongly associated with idiopathic membranous nephropathy in patients of European descent." (PMID 40363910, 2025). "In contrast, genetic variation in PLA2R1 has been associated with membranous nephropathy; a risk allele at HLA-DQA1 has also been associated with increased risks of various autoimmunity-associated diseases, but not IgAN17." (PMID 32820208, 2020). "In this study, we found several PLA2R1 and HLA-DQA1 single-nucleotide polymorphism loci associated with primary membranous nephropathy morbidity and that some PLA2R1 single-nucleotide polymorphism loci were related to the treatment response of patients with primary membranous nephropathy." (PMID 40845005, 2025). "Genotypic and allelic frequency distributions for six single-nucleotide polymorphisms within PLA2R1 (rs4664308, rs3792189, rs3792192, rs1870102, rs17831251, and rs35771982) and one in HLA-DQA1 (rs2187668) were associated with morbidity of primary membranous nephropathy." (PMID 40845005, 2025). "The purpose of this study was to observe the relationship between gene polymorphisms and primary membranous nephropathy and explore the clinical functional clues of PLA2R1 and HLA-DQA1 genes affecting treatment responsiveness." (PMID 40845005, 2025). "In membranous nephropathy, associated with massive proteinuria and which is common in adults, PLA2R and HLA-DQA1 regions are disease susceptibility genes." (PMID 35006356, 2022). "The aim of this study was to demonstrate the relationship between the PLA2R1 and HLA-DQA1 genes and PMN and to determine the clinical value of SNP in the treatment of primary membranous nephropathy." (PMID 40845005, 2025).
ulcerative colitis (7 papers, 2013 to 2025). An inflammatory bowel disease involving the mucosal surface of the large intestine and rectum. "In addition to HLA-DQA1*05:01 carriage, treatment for ulcerative colitis (UC), use as a subsequent (second line) biologic, and earlier era of treatment initiation were all independently associated with a shorter time to LoR to infliximab." (PMID 41388917, 2025).